ZNF20 (zinc finger protein 20)
Description:
May be involved in transcriptional regulation.
Synonyms: KOX13
Tractability: PROTAC: ubiquitination databases record sites on it.
Gene: Protein-coding gene on chromosome 19 (12,092,843 to 12,140,355, reverse strand). Ensembl gene ENSG00000132010.
Subcellular location: Nucleus
Subcellular location (Human Protein Atlas): Nuclear membrane; Nuclear bodies; Nucleoplasm
Pathways (Reactome):
Gene expression (Transcription): Generic Transcription Pathway
Gene Ontology:
Molecular function: protein binding; DNA-binding transcription factor activity, RNA polymerase II-specific; RNA polymerase II transcription regulatory region sequence-specific DNA binding; sequence-specific double-stranded DNA binding
Biological process: regulation of transcription by RNA polymerase II; regulation of DNA-templated transcription
Cellular component: nucleus
Genetic constraint (gnomAD): Loss-of-function variants: 9 observed, 11.64 expected, observed/expected ratio (o/e) 0.77, 90% interval 0.47 to 1.35. The upper end of that interval is the gene's LOEUF score, 1.35, which puts it in group 5 of 6, group 1 being the genes least tolerant of losing a copy. Missense variants: 528 observed, 673.81 expected, observed/expected ratio (o/e) 0.78, 90% interval 0.73 to 0.84. Synonymous variants: 182 observed, 225.06 expected, observed/expected ratio (o/e) 0.81, 90% interval 0.72 to 0.91.
Homologues: Orthologues: chimpanzee ZNF20 (99% identical), mouse Zfp78 (35% identical), Drosophila melanogaster CG3281 (23% identical), Drosophila melanogaster Phs (20% identical), Drosophila melanogaster CG2712 (20% identical). Paralogues in human: ZNF69 (61% identical), ZNF440 (55% identical), ZNF439 (53% identical), ZNF555 (47% identical), ZNF491 (45% identical), ZNF560 (44% identical), ZNF763 (42% identical), ZNF778 (41% identical), ZNF266 (41% identical), ZNF596 (40% identical), ZNF599 (39% identical), ZNF805 (39% identical), and 50 more.
Diseases named in the same sentence as ZNF20 in open-access papers:
ZNF20 is named in the same sentence as 4 diseases in open-access papers, as found by Europe PMC text mining. Sharing a sentence is not in itself a finding about the gene and the disease. The quoted sentences say what the papers report.
kidney diseases (1 paper, 2024). "They displayed CpG sites located near genes such as ZNF20 and ITGB2, which are known to be enriched for functional roles in kidney diseases." (PMID 38879526, 2024).
tumour (1 paper, 2023). "In the ZNF protein family, ZNF 471, ZNF1 and ZNF20 are involved in tumour progression through various pathways, including prognostic features, immune infiltration, TME, and tumour-related signalling pathways." (PMID 36803542, 2023).
ZNF20 also shares sentences with these, for which no sentence is quoted: glioma (1 paper); kidney failure (1).